MS4A10 (membrane spanning 4-domains A10)
Description:
May be involved in signal transduction as a component of a multimeric receptor complex.
Synonyms: CD20L7; MS4A9
Tractability: Antibody: UniProt predicts a signal peptide or a membrane-spanning region; its Gene Ontology location is reachable by antibodies, with medium confidence.
Gene: Protein-coding gene on chromosome 11 (60,785,333 to 60,801,305, forward strand). Ensembl gene ENSG00000172689.
Subcellular location: Membrane
Gene Ontology:
Molecular function: protein binding
Biological process: cell surface receptor signaling pathway
Cellular component: plasma membrane; membrane
Genetic constraint (gnomAD): Loss-of-function variants: 22 observed, 21.88 expected, observed/expected ratio (o/e) 1.01, 90% interval 0.72 to 1.43. The upper end of that interval is the gene's LOEUF score, 1.43, which puts it in group 5 of 6, group 1 being the genes least tolerant of losing a copy. Missense variants: 310 observed, 304.88 expected, observed/expected ratio (o/e) 1.02, 90% interval 0.93 to 1.12. Synonymous variants: 129 observed, 125.25 expected, observed/expected ratio (o/e) 1.03, 90% interval 0.89 to 1.19.
Homologues: Orthologues: chimpanzee MS4A10 (98% identical), macaque MS4A10 (61% identical), rabbit MS4A10 (53% identical), pig MS4A10 (52% identical), rat Ms4a10 (50% identical), mouse Ms4a10 (48% identical), zebrafish ms4a17a.17 (18% identical), zebrafish si:dkey-77f5.10 (17% identical), zebrafish ms4a17a.12 (16% identical), zebrafish ms4a17a.16 (16% identical), zebrafish ms4a17a.4 (16% identical), zebrafish ms4a17a.11 (16% identical), and 19 more. Paralogues in human: MS4A8 (21% identical), MS4A15 (19% identical), MS4A12 (18% identical), MS4A1 (17% identical), MS4A18 (17% identical), MS4A2 (16% identical), MS4A6A (16% identical), MS4A7 (15% identical), MS4A14 (15% identical), MS4A3 (14% identical), MS4A4A (14% identical), MS4A5 (12% identical), and 4 more.
Diseases named in the same sentence as MS4A10 in open-access papers:
MS4A10 is named in the same sentence as 1 disease in open-access papers, as found by Europe PMC text mining. Sharing a sentence is not in itself a finding about the gene and the disease. The quoted sentences say what the papers report.
tumor (1 paper, 2022). "Protein levels of MS4A10, MS4A8, MS4A7, PCNA, BAX, Bcl-2, Caspase-3, and cleaved Caspase-3 were measured in tumor tissues." (PMID 36438804, 2022).